SLC2A10 (solute carrier family 2 member 10)
Description:
Facilitative glucose transporter required for the development of the cardiovascular system.
Synonyms: GLUT-10; GLUT10; ATORS; ATS
Tractability: Antibody: its Gene Ontology location is reachable by antibodies, with high confidence; UniProt predicts a signal peptide or a membrane-spanning region. PROTAC: ubiquitination databases record sites on it; its protein half-life has been measured.
Gene: Protein-coding gene on chromosome 20 (46,709,577 to 46,736,347, forward strand). Ensembl gene ENSG00000197496.
Subcellular location: Endomembrane system; Cytoplasm, perinuclear region
Subcellular location (Human Protein Atlas): Cytosol
Pathways (Reactome):
Disease: Defective SLC2A10 causes arterial tortuosity syndrome (ATS)
Transport of small molecules: Cellular hexose transport
Gene Ontology:
Molecular function: D-glucose transmembrane transporter activity; dehydroascorbic acid transmembrane transporter activity; carbohydrate:proton symporter activity; transmembrane transporter activity
Biological process: artery development; cell redox homeostasis; D-glucose import across plasma membrane; dehydroascorbic acid transport; embryonic skeletal joint development; negative regulation of connective tissue growth factor production; negative regulation of gene expression; negative regulation of integrin-mediated signaling pathway; negative regulation of proteoglycan biosynthetic process; negative regulation of transforming growth factor beta receptor signaling pathway; positive regulation of gene expression; positive regulation of proteoglycan biosynthetic process; positive regulation of transforming growth factor beta receptor signaling pathway; regulation of extracellular matrix organization; skin development; circulatory system development; D-glucose transmembrane transport; galactose transmembrane transport; hexose transmembrane transport; transport across blood-brain barrier; animal organ development; proton transmembrane transport; transmembrane transport
Cellular component: cytosol; endomembrane system; perinuclear region of cytoplasm; plasma membrane; membrane
Genetic constraint (gnomAD): Loss-of-function variants: 27 observed, 34.24 expected, observed/expected ratio (o/e) 0.79, 90% interval 0.58 to 1.09. The upper end of that interval is the gene's LOEUF score, 1.09, which puts it in group 4 of 6, group 1 being the genes least tolerant of losing a copy. Missense variants: 673 observed, 721.79 expected, observed/expected ratio (o/e) 0.93, 90% interval 0.87 to 0.99. Synonymous variants: 332 observed, 325.53 expected, observed/expected ratio (o/e) 1.02, 90% interval 0.93 to 1.12.
Gene-disease validity (ClinGen):
ClinGen rates the evidence that SLC2A10 causes each of these diseases.
arterial tortuosity syndrome (autosomal recessive): Definitive. Arterial tortuosity syndrome (ATS) is a rare connective tissue disorder characterized by tortuosity and elongation of the large and medium-sized arteries and a propensity towards aneurysm formation, vascular dissection, and stenosis of the pulmonary arteries.
Homologues: Orthologues: chimpanzee SLC2A10 (99% identical), macaque SLC2A10 (96% identical), pig SLC2A10 (84% identical), dog SLC2A10 (84% identical), guinea pig SLC2A10 (81% identical), mouse Slc2a10 (77% identical), rat Slc2a10 (77% identical), rabbit SLC2A10 (57% identical), tropical clawed frog slc2a10 (55% identical), zebrafish slc2a10 (43% identical), Caenorhabditis elegans fdgt-1 (23% identical), Drosophila melanogaster Tret1-1 (23% identical), and 40 more. Paralogues in human: SLC2A12 (40% identical), SLC2A13 (26% identical), SLC2A6 (25% identical), SLC2A8 (24% identical), SLC2A2 (23% identical), SLC2A7 (23% identical), SLC2A1 (23% identical), SLC2A4 (23% identical), SLC2A5 (23% identical), SLC2A3 (22% identical), SLC2A14 (22% identical), SLC2A11 (21% identical), and 1 more.
Diseases named in the same sentence as SLC2A10 in open-access papers:
SLC2A10 is named in the same sentence as 53 diseases in open-access papers, as found by Europe PMC text mining. Sharing a sentence is not in itself a finding about the gene and the disease. The quoted sentences say what the papers report.
arterial tortuosity syndrome (9 papers, 2010 to 2025). "Two other pathogenic heterozygous variants (one de novo and the other a known mutation) in the SLC2A10 gene (compound heterozygous genotype) were identified in a patient diagnosed with arterial tortuosity syndrome (ATORS)." (PMID 39456956, 2024). "GLUT10 is encoded by the SLC2A10 gene, and mutations in SLC2A10 result in hereditary arterial tortuosity syndrome (ATS)." (PMID 36873535, 2023). "Loss-of-function mutations in glucose transporter 10 (GLUT10) gene (SLC2A10) lead to a rare autosomal recessive connective tissue disorder called arterial tortuosity syndrome (ATS; OMIM 208,050)." (PMID 35842612, 2022). "As GLUT10 is localised to the mitochondria in vascular smooth muscle cells and mutations of the SLC2A10 gene are associated with arterial tortuosity syndrome, more work is now required to elucidate this potentially distinct role of GLUT10 in the airway." (PMID 24810961, 2014). "Arterial tortuosity syndrome is a rare Autosomal recessive disease that leads to a loss of function of the connective tissues of the body, this happens due to a mutation in the solute carrier family 2 member 10 (SLC2A10) gene." (PMID 38987788, 2024). "Recent data indicate that loss-of-function mutation in the gene encoding the facilitative glucose transporter GLUT10 (SLC2A10) causes arterial tortuosity syndrome via upregulation of the TGF-β pathway in the arterial wall, a mechanism possibly causing vascular changes in diabetes." (PMID 20735855, 2010). "Recently, a genetic form of arterial tortuosity syndrome (ATS; OMIM 208050) was reported to be caused by loss-of-function mutations in the SLC2A10 gene encoding the facilitative glucose transporter GLUT10." (PMID 20735855, 2010).
diabetes (3 papers, 2010 to 2021). "Genes such as KCNE2, DLL1, ACVR1C, RGS3, MLXIPL (MLX interacting protein like), PAG1, SLC2A10 and GRB14 play important role in type 2 diabetes mellitus progression." (PMID 33902539, 2021). "Moreover, power analysis showed that there might be a lack of power for the meta- analysis of SLC2A10 rs2335491 (1,455 cases and 1,083 controls, 39%) under a moderate risk of diabetes (OR = 1.2)." (PMID 23922971, 2013).
type 2 diabetes (3 papers, 2005 to 2021). "Our data demonstrate that genetic polymorphism of the SLC2A10 gene is an independent risk factor for PAD in type 2 diabetes." (PMID 20735855, 2010). "Our results demonstrate that variation of the SLC2A10 gene not only results in a rare vascular syndrome but also is associated with susceptibility to common vascular complications in type 2 diabetes." (PMID 20735855, 2010). "GLUT10 (gene symbol SLC2A10) is a facilitative glucose transporter within the type 2 diabetes (T2DM)-linked region on chromosome 20q12-13.1." (PMID 16336637, 2005). "SLC2A10 haplotype analysis for association with baseline, incident, and all PAD in type 2 diabetes." (PMID 20735855, 2010). "Multivariate regression analyses of the SLC2A10 haplotype H4 with PAD in type 2 diabetes." (PMID 20735855, 2010).
breast carcinoma (2 papers, 2014 to 2023). "The SLC2A10 expression level was significantly correlated with worse survival in several cancers, including brain cancer, breast cancer, lung cancer, colorectal cancer, eye cancer, skin cancer, and soft tissue cancer, while it was slightly correlated with worse survival in ovarian cancer." (PMID 36873535, 2023). "SLC2A10 was expressed at lower levels than in normal tissue in colorectal cancer, head and neck cancer, liver cancer, and melanoma but expressed at higher levels than in normal tissue in bladder cancer, brain and central nervous system cancer, breast cancer, kidney cancer, lymphoma and sarcoma." (PMID 36873535, 2023).
COVID-19 (2 papers, 2023 to 2025). A disease caused by infection with severe acute respiratory syndrome coronavirus 2. "The study found that autoantigens like NXPH-1, PCSK-1, SLC2A10, and DCD correlated with markers of COVID-19 severity like D-dimers, ferritin, C-reactive protein, and lactate which can increase in severe COVID-19." (PMID 36937488, 2023).
glioblastoma (2 papers, 2022 to 2024). The most malignant astrocytic tumor (WHO grade IV). "Among these SLCs, SLC2A10 has been reported to be associated with ferroptosis in glioblastoma, SLC47A1 has been demonstrated to mediate temozolomide resistance in glioblastoma, while the functions of the other SLCs in glioblastoma remain unclear." (PMID 38687049, 2024).
lung carcinoma (2 papers, 2022 to 2023). "Among all cancer types, the survival of lung cancer patients is most strongly affected by SLC2A10 expression." (PMID 36873535, 2023). "Remarkably, we found that regardless of what type of survival (OS, PPS, FP) was considered, the prognosis of lung cancer was significantly related to the expression level of SLC2A10." (PMID 36873535, 2023). "To further investigate the relationship between SLC2A10 and lung cancer immunity, we used TIMER and GEPIA to explore the correlation between gene expression and immune marker sets of various immune cells of LUAD and LUSC." (PMID 36873535, 2023). "Lung cancer patients with low expression of SLC2A10 have a much shorter median survival time than patients with high expression of SLC2A10." (PMID 36873535, 2023). "Regardless of the type of survival (OS, PPS, FP), lower expression of SLC2A10 predicts the worst prognosis of lung cancer." (PMID 36873535, 2023). "Patients with low expression of SLC2A10 in lung cancer had a much shorter median survival time than patients with high expression of SLC2A10." (PMID 36873535, 2023). "Low SLC2A10 expression was related to poorer prognosis and increased malignancy of lung cancer." (PMID 36873535, 2023). "In this study, we used the public databases Oncomine, PrognoScan, Kaplan‒Meier Plotter, TIMER and GEPIA and IFC (immunofluorescence) of lung cancer specimens to further investigate the potential prognostic value and immunological roles of SLC2A10 expression in tumors." (PMID 36873535, 2023). "Downregulated levels of SLC2A10 in lung cancer indicate a poor prognosis and increased aggressiveness of tumors, suggesting that SLC2A10 may play a crucial role in the progression of cancer." (PMID 36518662, 2022).
Marfan syndrome (2 papers, 2014 to 2022). A disorder of the connective tissue. "Variants in the glucose transport 10 protein, Glut10 (encoded by SLC2A10), have been associated with a Marfan syndrome-like disease pathology that is seen in arterial tortuosity syndrome, another disease associated with aortic dissections." (PMID 36561772, 2022). "Variants in CBS are associated with the metabolic condition, homocystinuria, which, similar to pathogenic SLC2A10 variants, can result in a Marfan syndrome-like disease pathology." (PMID 36561772, 2022).
acute myeloid leukemia (1 paper, 2023). Acute myeloid leukemia (AML) is a group of neoplasms arising from precursor cells committed to the myeloid cell-line differentiation. "Recent research also discovered that SLC2A10 expression levels may be a useful prognostic biomarker in acute myeloid leukemia." (PMID 36873535, 2023).
bladder cancer (1 paper, 2023). "SLC2A10 is expressed at low levels in colon adenocarcinoma, head and neck squamous cell carcinoma, kidney chromophobe, thyroid carcinoma, and uterine corpus endometrial carcinoma but is highly expressed in bladder cancer." (PMID 36873535, 2023).
breast tumors (1 paper, 2023). "Specifically, SLC2A1, SLC2A6, SLC2A10, and SLC2A13 were significantly overexpressed, whereas SLC2A3, SLC2A4, SLC2A9, SLC2A11, and SLC2A12 had downregulated expressions in breast tumors compared with those in normal breast epithelium." (PMID 37108300, 2023).
central nervous system cancer (1 paper, 2023). "As the figure shows, the SLC2A10 expression level correlates with poorer prognosis and high immune infiltrates in colon adenocarcinoma (COAD), kidney renal clear cell carcinoma (KIRC), lower grade glioma (LGG) and rectum adenocarcinoma (READ)." (PMID 36873535, 2023).
dyslipidemia (1 paper, 2021). "However, there are reports on six of Slc genes (Slc2a10, Slc5A1, Slc5a9, Slc6A14, Slc16A5, Slc25A24) in metabolic diseases including obesity, dyslipidemia, NAFLD, and T2DM." (PMID 34659115, 2021).
leukemia (1 paper, 2024). A malignant (clonal) hematologic disorder, involving hematopoietic stem cells and characterized by the presence of primitive or atypical myeloid or lymphoid cells in the bone marrow and the blood. "Another study reported that SLC2A10 could be a target of lncRNA H22954, which inhibited GLUT10 expression and glucose uptake in leukemia cells." (PMID 38688953, 2024).
uterus adenocarcinoma (1 paper, 2020). "The fold change in expression of SLC2A10 was 1.10 in a uterus adenocarcinoma sample with a BA-deletion compared with the rest of uterus tumor samples." (PMID 32024999, 2020).
cancer (5 papers, 2022 to 2023). A tumor composed of atypical neoplastic, often pleomorphic cells that invade other tissues. "In these results, we further found that SLC2A10 expression was significantly associated with the level of immune infiltrates in 10 types of these cancers." (PMID 36873535, 2023). "Then, we studied the expression level of SLC2A10 in cancers by the Oncomine database and Tumor Immune Estimation Resource (TIMER) site." (PMID 36873535, 2023). "It is interesting that SLC2A10 expression is significantly correlated with macrophage polarization in cancers." (PMID 36873535, 2023). "We also evaluated the prognostic potential of SLC2A10 in different cancers using the Kaplan‒Meier plotter database and PrognoScan online software." (PMID 36873535, 2023). "We found that SLC2A10 expression in carcinoma samples was significantly different from that in adjacent tissues." (PMID 36873535, 2023). "We screened 62 SWEETs in pan-cancer and found that they highly expressed with worse survival SLC2A10 as a critical biomarker in GBM and related to the NRF2 signalling pathway." (PMID 35962317, 2022). "To give a more evident plot of the response of significantly highly expressed with poorly prognostic DE-SWEETs in pan-cancer, we redrawn the sanger plot and found that only SLC2A10 was significantly highly expressed with poor prognosis in GBM." (PMID 35962317, 2022). "To evaluate whether SLC2A10 impacts the prognosis of cancer patients, we analysed the correlation between the SLC2A10 expression level and patient survival using PrognoScan online software." (PMID 36873535, 2023). "We found that SLC2A10 expression had significant correlations with tumor purity in 5 types of cancers and significant correlations with macrophage infiltration levels in 22 types of cancers." (PMID 36873535, 2023). "Furthermore, the expression of SLC2A10 was significantly correlated with the infiltration levels of DCs in 19 types of cancers, neutrophils in 16 types of cancers, CD8+ T cells in 13 types of cancers, and CD4+ T cells and B cells in 11 types of cancers." (PMID 36873535, 2023). "The expression level of SLC2A10 is closely correlated with cancer prognosis." (PMID 36873535, 2023). "The expression level of SLC2A10 was closely correlated with cancer prognosis." (PMID 36873535, 2023). "SLC2A10 expression in cancer cell lines and tumors is unknown." (PMID 37108300, 2023). "However, less is known about the implications of SLC2A10 overexpression in cancer." (PMID 36463288, 2022).
tumor (4 papers, 2022 to 2024). "The differential expression of SLC2A10 between tumor and adjacent normal tissues across all TCGA tumors was compared." (PMID 36873535, 2023). "However, GLUT10 acts as a member of the glucose transporter family, and few studies have focused on the relationship between SLC2A10 expression and tumor immunity." (PMID 36873535, 2023). "Additionally, lower levels of SLC2A3, SLC2A6, SLC2A9, SLC2A12, and SLC2A14 and higher levels of SLC2A1, SLC2A5, SLC2A10, and SLC2A11 had an association with advanced tumor stage." (PMID 36518662, 2022). "The results indicate that SLC43A3, SLC25A43, SLC2A10 and SLC47A1 show sporadic expression in both tumour cells and TAMs." (PMID 38687049, 2024). "According to data from the UALCAN database, LUAD patients’ tumor tissues had hypomethylation of SLC2A1, SLC2A2, SLC2A5, SLC2A6, SLC2A7, SLC2A11 and hypermethylation of SLC2A3, SLC2A10, and SLC2A14 compared to normal tissues." (PMID 36518662, 2022). "SLC2A1, SLC2A5, SLC2A10, and SLC2A11 levels tended to be higher in patients with advanced tumor stages, which shows that these molecules may be involved in the development of malignancies in LUAD patients." (PMID 36518662, 2022). "A lower differentiation grade tumor is implied by overexpression of SLC2A1, SLC2A5, SLC2A10, SLC2A11and lower levels of SLC2A3, SLC2A6, SLC2A9, SLC2A12, and SLC2A14, emphasizing the possibility of these molecular roles for predicting the course of the tumor." (PMID 36518662, 2022). "The expression of EMP3, GSAP, SLC2A10, and SWAP70 was higher in tumor periphery." (PMID 36727078, 2022). "Interestingly, similar to the results obtained from bulk analysis, the single‐cell data showed a higher detection of SLC43A3, SLC2A10, SLC25A43, SLC7A7 and SLC47A1, which are highly expressed in tumour tissues, relative to SLC1A6 and SLC24A4, which are lowly expressed." (PMID 38687049, 2024). "The results demonstrated significantly higher expression of SLC43A3 and SLC2A10 in tumour slices compared to adjacent non‐cancerous tissue slice, with almost no detectable expression of SLC1A6 in the tumour slices." (PMID 38687049, 2024).
vasculopathies (1 paper, 2014). "Similar to other conditions known as TGF-β vasculopathies (MFS, which is caused by FBN1 mutations and LDS, which is caused by TGFBR1, TGFBR2, SMAD3 and TGFB2 mutations), the SLC2A10 loss of function activates the TGF-β signaling pathway." (PMID 25373504, 2014).
SLC2A10 also shares sentences with these, for which no sentence is quoted: Aortic dissection (2 papers); connective tissue disorder (2); aortic aneurysm (1); brain cancer (1); colon adenocarcinoma (1); colorectal cancer (1); esophageal adenocarcinoma (1); eye cancer (1); gastric cancer (1); glioma (1); head and neck cancer (1); head and neck squamous cell carcinoma (1); Insulin resistance (1); kidney cancer (1); liver cancer (1); Loeys-Dietz syndrome (1); lymphoma (1); melanoma (1); metabolic disease (1); Obesity (1); osteomyelitis (1); ovarian carcinoma (1); pancreatic ductal adenocarcinoma (1); peripheral arterial disease (1); prostate adenocarcinoma (1); rectum adenocarcinoma (1); sarcoma (1); Seckel syndrome (1); skin cancer (1); stomach adenocarcinoma (1).
A further 5 diseases each share a sentence with SLC2A10 in 1 paper.